RBBP4 (RB binding protein 4, chromatin remodeling factor)
Diseases named in the same sentence as RBBP4 in open-access papers (continued):
Sharing a sentence is not in itself a finding about the gene and the disease.
lung carcinoma (6 papers, 2020 to 2025). "Analysis of the TCGA database revealed that heightened expression of RBBP4 was associated with unfavorable survival outcomes in patients with lung cancer." (PMID 38034873, 2023). "TCGA database showed that RBBP4 was significantly upregulated in lung cancer and was associated with poor patient prognosis." (PMID 38034873, 2023). "To determine the potential prognostic significance of RBBP4 in lung cancer, we examined the association between RBBP4 expression and overall survival (OS), first progression survival (FP), and post-progression survival (PPS) using the Kaplan–Meier mapper plotter database." (PMID 38034873, 2023). "These ropivacaine-induced changes may be associated with reduced RBBP4 expression, thus providing a novel theoretical reference and scientific basis for the use of ropivacaine in the treatment of lung cancer." (PMID 38034873, 2023). "In this study, cisplatin was found to induce RBBP4 expression in human lung cancer A549 cells, and RBBP4 expression in cisplatin-resistant A549/DDP cells was significantly higher than in A549 cells." (PMID 40187236, 2025). "We observed elevated RBBP4 expression in NSCLC tissues, in accordance with prior findings of its upregulation in NSCLC tumors, which suggests that RBBP4 has a potential oncogenic role in lung cancer." (PMID 39109577, 2024). "To confirm RBBP4 levels in tumor cells, we investigated RBBP4 expression in three lung cancer cell lines, namely, PC9, H1299, and A549." (PMID 39109577, 2024). "Concurrently, in vitro cytological investigations revealed that suppression of RBBP4 led to a reduction in the proliferation and invasiveness of lung cancer cells." (PMID 38034873, 2023). "Our study provides evidence that ropivacaine inhibits the malignant behavior of A549 and H1299 lung cancer cells by regulating retinoblastoma binding protein 4 (RBBP4)." (PMID 38034873, 2023). "Consistent with the changes in MTS, the results from flow cytometry showed that RBBP4 knockdown combined with ropivacaine treatment induced cell cycle arrest at the G0/G1 phase in lung cancer cells, which was the most remarkable among the four groups." (PMID 38034873, 2023). "Conversely, the upregulation of RBBP4 demonstrated the opposite effect, indicating its oncogenic role in the progression of lung cancer." (PMID 38034873, 2023). "To examine the biological role of RBBP4 in lung cancer cells, we used siRNA-mediated gene silencing to knock down RBBP4." (PMID 38034873, 2023). "Considering that RBBP4 knockdown suppressed the proliferation of A549 and H1299 lung cancer cells, we further explored its effect on the cell cycle." (PMID 38034873, 2023). "Our results showed that RBBP4 protein expression levels were significantly downregulated in a contraction-related manner in the ropivacaine-treated group compared to the control group, indicating that ropivacaine reduced RBBP4 expression in lung cancer cells." (PMID 38034873, 2023). "Overexpression and knockdown of RBBP4 significantly altered the antitumor effects of ropivacaine on the malignant behavior of lung cancer cells." (PMID 38034873, 2023). "Inhibition of RBBP4 by siRNA resulted in a significant decrease in the proliferation and invasive capacity of lung cancer cells and the induction of cell cycle arrest." (PMID 38034873, 2023). "To fully investigate the potential involvement of RBBP4 in the pathogenesis of lung cancer, we first analyzed the expression levels of this gene across 33 cancer datasets obtained from the TCGA database." (PMID 38034873, 2023). "We further investigated the impact of RBBP4 knockdown on lung cancer cell migration and invasion using Transwell assays." (PMID 38034873, 2023). "High RBBP4 expression predicts poor survival outcome in patients with lung cancer." (PMID 38034873, 2023).
lung carcinoma (continued). "Our data suggest that ropivacaine suppresses lung cancer cell malignancy by downregulating RBBP4 protein expression, which may help clarify the mechanisms underlying the antitumor effects of ropivacaine." (PMID 38034873, 2023). "The present study aimed to determine whether ropivacaine modulates the biological function of lung cancer cells through RBBP4." (PMID 38034873, 2023). "In vivo and in vitro validation confirmed the role of RBBP4 in autophagy‐mediated cell death in NSCLC, providing insights into its mechanistic impact on lung cancer cells." (PMID 39109577, 2024). "Finally, RBBP4, a downregulated DEP, was selected for post-validation among the candidates and is considered to play a crucial role in the antitumor effect of ropivacaine in lung cancer cells." (PMID 38034873, 2023).
neuroblastoma (6 papers, 2014 to 2024). Neuroblastoma (NB) is the most common solid, extracranial childhood tumor. "Rbbp4 was also shown to be required for tumor progression in neuroblastoma xenografts by PRC2 silencing of tumor suppressors." (PMID 35266256, 2022). "In relation to this, ARMC12 is known to interact with nuclear protein RBBP4 to facilitate tumorigenesis of neuroblastoma." (PMID 33536340, 2021). "It has been found that blocking the interaction between ARMC12 and RBBP4 by cell‐penetrating inhibitory peptides can activate the expression of downstream genes and inhibit the tumorigenesis and invasiveness of neuroblastoma cells." (PMID 32564518, 2020). "Here, the authors show that a new ARM protein (ARMC12) is upregulated in neuroblastoma, binds the PRC2 component RBBP4, and inhibits transcription of tumor suppressive genes." (PMID 30026490, 2018).
hepatocellular carcinoma (5 papers, 2021 to 2025). A malignant tumor that arises from hepatocytes. "SALL4 in hepatocellular carcinoma cells silences tumor suppressor genes through RBBP4/7 binding to NuRD." (PMID 38028543, 2023). "A prognostic factor miRNA in hepatocellular carcinoma, miR-429, directly targets RBBP4 and reduces RBBP4 expression." (PMID 38028543, 2023). "Liver tumor-initiating cells are critical for hepatocarcinogenesis, and RBBP4 is particularly critical for48 maintaining the stemness of hepatocellular carcinoma cells." (PMID 38028543, 2023). "For example, Kaplan–Meier curves indicated that hepatocellular carcinoma (LIHC) high expression groups for both RBBP4 and RBBP7 had significantly worse overall survival (P < 0.01) compared with low expression groups." (PMID 34086947, 2021). "Similarly, RBBP4 has been found to be overexpressed in hepatocellular carcinoma and acute myeloid leukemia." (PMID 34086947, 2021). "In the literature review, it was reported that RBBP4, a subunit of the NURF complex, facilitated hepatocellular carcinoma by interacting with other components to silence tumor suppressor genes." (PMID 33430870, 2021). "However, the RBBP4 subunit can also bind to SALL4 and subsequently recruit the NuRD complex to the promoters of tumor suppressors and silence their expression, thereby promoting hepatocellular carcinoma cell survival." (PMID 38028543, 2023).
thyroid cancer (5 papers, 2010 to 2025). "In thyroid cancer, RBBP4 promotes the growth potential of cancer cells through influencing the functions of genes controlling cell cycle progression." (PMID 30026490, 2018). "Overexpression of RBBP4 is found in several cancer types such as thyroid carcinomas." (PMID 38827131, 2024).
cervical cancer (4 papers, 2018 to 2025). A primary or metastatic malignant neoplasm involving the cervix. "The previous study has shown that downregulated RBBP4 expression inhibits Epithelial Mesenchymal Transition (EMT) in MS751 human cervical cancer cells." (PMID 40187236, 2025). "The intersection of LASSO and SVM-RFE analyses revealed eight hub genes in cervical cancer, which were RBBP4, SRM, GCH1, USP14, TRAIP, CBX4, VEZF1, and TOM1." (PMID 36999051, 2023). "Unusually, RBBP4 tends to be downregulated in cervical cancer, and downregulation of RBBP4 can even induce cervical mucosa epithelial cell carcinogenesis." (PMID 38028543, 2023). "On the other hand, different expression of RBBP4 in cervical cancer produced differences in cell proliferation after irradiation." (PMID 38028543, 2023). "More importantly, the expression levels of the key oncogenes E6 and E7 in cervical cancer can increase by 8-fold and 28-fold respectively after RBBP4 knockdown." (PMID 38028543, 2023). "This study further reveals that RBBP4 can regulate cisplatin sensitivity by modulating cyclin D1 expression, consistent with previous findings that RBBP4 knockdown inhibits epithelial-mesenchymal transition in cervical cancer cells." (PMID 40187236, 2025). "Among these genes in the prognostic gene signature, it has been confirmed that RBBP4 could control HPV16 transforming activity in cervical cancer." (PMID 36999051, 2023).
breast tumors (3 papers, 2019 to 2025). "While SUZ12, RBBP4 and RBBP7 were highly expressed in breast tumors, their transcription levels were either comparable to or lower in TNBC groups compared to non-TNBC groups." (PMID 41413688, 2025). "SIN3B, HDAC1, HDAC2, SUDS3, and RBBP4, but not SIN3A and SAP18, were also upregulated to a lesser degree in human breast tumors." (PMID 37655663, 2023). "We further found that mRNAs of SAP30, HDAC1, RBBP4, and RBBP7 but not other core subunits were significantly induced in all 4 major subtypes of breast tumors." (PMID 37655663, 2023).
gastric cancer (3 papers, 2021 to 2025). A primary or metastatic malignant neoplasm involving the stomach. "In another study, RBBP4 silencing impaired the proliferation of gastric cancer cells but stimulated apoptosis." (PMID 33430870, 2021).
leukemia (3 papers, 2021 to 2024). A malignant (clonal) hematologic disorder, involving hematopoietic stem cells and characterized by the presence of primitive or atypical myeloid or lymphoid cells in the bone marrow and the blood. "Our findings regarding elevated expression of Hdac3 and Rbbp4 in fetal but not adult pre-leukemic cells compared to WT may also have implications for the design of treatment schemes involving HDAC inhibitors for infant and adult leukemia." (PMID 38555405, 2024).
brain cancer (2 papers, 2018 to 2022). A primary or metastatic malignant neoplasm affecting the brain. "Elevated RBBP4 expression was detected in tissues from many embryonal central nervous system primitive neuroectodermal tumors (CNS‐PNETs) and malignant brain cancers, including ependymal, glial, oligodendroglial, and astrocytic tumors." (PMID 35266256, 2022). "To investigate whether human RBBP4 is upregulated in human embryonal tumors and other aggressive pediatric and adult brain cancers we examined RBBP4 expression data from 2284 human brain tumor samples from the German Cancer Research Center." (PMID 35266256, 2022). "Our study provides new insight into the epigenetic processes that might drive pathogenesis in RB1 brain tumors, and identifies Rbbp4 and its associated chromatin remodeling complexes as potential target pathways to induce apoptosis in RB1 mutant brain cancer cells." (PMID 29914980, 2018). "Together with the survival-promoting activity of RBBP4, HDAC1 and RBBP4 might cooperate to drive persistent proliferation and growth of tumor cells in RB1 mutant brain cancer." (PMID 29914980, 2018).
brain tumor (2 papers, 2018 to 2022). "A similar epigenetic mechanism in which Hdac1 and Rbbp4 associate with oligoneural precursor transcription factors might drive zebrafish rb1 brain tumor oncogenesis." (PMID 29914980, 2018). "Given the important contributions of developmental and cell cycle control mechanisms in cancer, a more detailed examination of the role of Rbbp4 in neural progenitor cell cycle regulation would provide insight into its possible oncogenic roles in brain tumors." (PMID 35266256, 2022). "Examining the contribution of HDAC1 and RBBP4 to maintaining the progenitor-like state of RB1 brain tumors would shed light on the mechanism of chromatin remodeling in epigenetic control of tumor suppression." (PMID 29914980, 2018). "Together these results show that elevated RBBP4 is a common signature in aggressive central nervous system tumors and suggest that Rbbp4 may contribute to oncogenesis by promoting brain tumor cell survival." (PMID 35266256, 2022). "In both zebrafish Rb germline mutants and Rb‐defective brain tumors, Rbbp4 is overexpressed, suggesting Rbbp4 adopts oncogenic properties in the absence of Rb." (PMID 35266256, 2022).
esophageal cancer (2 papers, 2022 to 2025). A primary or metastatic malignant neoplasm involving the esophagus. "The expression level of RBBP4 was upregulated in esophageal carcinoma according to GEPIA database." (PMID 36418920, 2022). "Reduced RBBP4 expression partially reversed the enhanced proliferation, migration, and invasion ability induced by overexpression of KTN1-AS1, indicating that the effect of KTN1-AS1 on the malignant behavior of esophageal cancer cells is affected by RBBP4." (PMID 36418920, 2022).
glial tumor (2 papers, 2022 to 2023). "It has been claimed that RBBP4 is upregulated in gliomas by targeting of the HOXA-AS2/miR-885–5p/RBBP4 axis, whereby the viability of malignant cells can be enhanced." (PMID 38028543, 2023).
microcephaly (2 papers, 2022). A congenital or acquired developmental disorder in which the circumference of the head is smaller than normal for the person's age and sex. "Loss of Rbbp4 leads to apoptosis throughout the 2 day post‐fertilization (dpf) brain and retina, resulting in microcephaly and microphthalmia." (PMID 35266256, 2022).
non-small cell lung carcinoma (2 papers, 2023 to 2024). A group of at least three distinct histological types of lung cancer, including non-small cell squamous cell carcinoma, adenocarcinoma, and large cell carcinoma. "Dysregulated expression of RBBP4 is associated with metastasis and unfavorable prognosis in highly aggressive and metastatic cancers, such as non-small cell lung cancer cells." (PMID 38034873, 2023).
pancreatic cancer (2 papers, 2024 to 2025). "The overall results suggest that miR-6794-3p inhibits methylation of histone H3 by suppressing RBBP4 expression, thereby uncovering a potential mechanism underlying the involvement of histone H3 methylation in invasion and migration of pancreatic cancer cells." (PMID 39430246, 2024). "Our collective findings suggest that miR-6794-3p regulates invasion and migration of pancreatic cancer cells through targeting the RBBP4/GRHL2 signaling pathway." (PMID 39430246, 2024). "Our collective findings support the notion that miR-6794-3p acts as a tumor suppressor in pancreatic cancer cells through targeting RBBP4." (PMID 39430246, 2024). "Both methylation of histone H3 and RBBP4 expression in pancreatic cancer cells were significantly inhibited by miR-6794-3p while GSK126 only inhibited histone H3 methylation." (PMID 39430246, 2024). "We also investigated whether miR-6794-3p-inhibited RBBP4 signaling could regulate the invasion and migration of pancreatic cancer cells by modulating GRHL2 expression." (PMID 39430246, 2024). "Here, we examined the hypothesis that miR-6794-3p-mediated inhibition of RBBP4 enhances histone H3 acetylation, leading to increased expression of epithelial markers and, consequently, inhibition of pancreatic cancer cell invasion and migration." (PMID 39430246, 2024). "Accordingly, we examined whether miR-6794-3p regulates GRHL2-mediated pancreatic cancer cell invasion and migration through regulatory effects on RBBP4." (PMID 39430246, 2024). "Our experiments designed to determine whether miR-6794-3p-regulated RBBP4 participates in nucleosome remodeling revealed that the miR-6794-3p-mediated suppression of RBBP4 effectively inhibited H3K27 acetylation in pancreatic cancer cells." (PMID 39430246, 2024). "Next, we determined whether miR-6794-3p-mediated inhibition of RBBP4 expression exerts a regulatory effect on GRHL2 in pancreatic cancer cells." (PMID 39430246, 2024). "However, the specific role of RBBP4 in pancreatic cancer cell invasion and migration is yet to be elucidated." (PMID 39430246, 2024). "The resulting suppression of RBBP4 induced an increase in the levels of GRHL2 involved in regulating invasion, migration, and EMT signaling in metastatic pancreatic cancer cells." (PMID 39430246, 2024). "Mechanistic analyses revealed that miR-6794-3p inhibits RBBP4 by directly binding to the 3′-UTR of RBBP4 and thereby upregulating GRGL2 to suppress pancreatic cancer cell invasion, migration, and metastasis." (PMID 39430246, 2024). "Based on our collective results, we conclude that miR-6794-3p modulates tumor growth via regulation of RBBP4/GRHL2 signaling, and has considerable value as a potential biomarker of metastasis in pancreatic cancer." (PMID 39430246, 2024). "We further investigated whether miR-6794-3p-mediated inhibition of RBBP4 expression enhances the GRHL2-induced increase in expression of epithelial markers and decrease in invasion and migration in pancreatic cancer cells." (PMID 39430246, 2024). "In pancreatic cancer, in contrast, no previous study had identified an RBBP4-targeting miRNA with implications in cancer cell invasion and migration." (PMID 39430246, 2024). "However, to our knowledge, no RBBP4-targeting miRNAs involved in tumor cell invasion and migration have been identified in pancreatic cancer." (PMID 39430246, 2024).
prostate adenocarcinoma (2 papers, 2021). "Through the TCGA database analysis, RBBP4/7 and BPTF is simultaneously overexpressed in ESCA, LIHC, STAD etc. and downregulated in KIRC, KICH, kidney renal papillary cell carcinoma (KIRP) and prostate adenocarcinoma (PRAD)." (PMID 34736517, 2021).
psoriasis (2 papers, 2022 to 2025). An autoimmune condition characterized by red, well-delineated plaques with silvery scales that are usually on the extensor surfaces and scalp. "Our analysis showed differential expression of EED, EZH1/2, and RBBP4 in the PRC2 complex, likely to affect stem cell self-renewal and possibly contributing to keratinocyte hyperproliferation in psoriasis." (PMID 40650108, 2025). "However, there is no direct evidence that RBBP7 or RBBP4 is correlated with psoriasis." (PMID 35669784, 2022).
acute leukemia (1 paper, 2024). A clonal (malignant) hematopoietic disorder with an acute onset, affecting the bone marrow and the peripheral blood. "In a previous study, higher RBBP4 levels were noted in acute leukemia and blast crisis chronic myeloid leukemia than in non‐leukemic states and the chronic phase of chronic myeloid leukemia, suggesting an association with malignancy progression." (PMID 39109577, 2024).
autism (1 paper, 2024). Persistent deficits in social interaction and communication and interaction as well as a markedly restricted repertoire of activity and interest as well as repetitive patterns of behavior. "Putative risk variants in RBBP4 have been associated with deficits in neuro-cognitive capacities in autism patients." (PMID 39592227, 2024).